ANHX (anomalous homeobox)
Tractability: No criterion of Open Targets' tractability assessment is met for any kind of drug.
Gene: Protein-coding gene on chromosome 12 (133,218,312 to 133,235,877, reverse strand). Ensembl gene ENSG00000227059.
Subcellular location: Nucleus
Gene Ontology:
Molecular function: DNA-binding transcription factor activity, RNA polymerase II-specific; RNA polymerase II cis-regulatory region sequence-specific DNA binding; DNA binding
Biological process: regulation of transcription by RNA polymerase II; regulation of DNA-templated transcription
Cellular component: nucleus; transcription regulator complex
Genetic constraint (gnomAD): Loss-of-function variants: 21 observed, 38.95 expected, observed/expected ratio (o/e) 0.54, 90% interval 0.38 to 0.78. The upper end of that interval is the gene's LOEUF score, 0.78, which puts it in group 3 of 6, group 1 being the genes least tolerant of losing a copy. Missense variants: 473 observed, 492.24 expected, observed/expected ratio (o/e) 0.96, 90% interval 0.89 to 1.04. Synonymous variants: 185 observed, 206.76 expected, observed/expected ratio (o/e) 0.89, 90% interval 0.79 to 1.01.
Homologues: Orthologues: chimpanzee ANHX (78% identical), macaque ANHX (74% identical), dog ANHX (71% identical), rabbit ANHX (71% identical), zebrafish six4b (16% identical), zebrafish six7 (15% identical), Drosophila melanogaster Optix (14% identical), Caenorhabditis elegans ceh-32 (14% identical), zebrafish six4a (14% identical), Caenorhabditis elegans ceh-34 (13% identical), Drosophila melanogaster Six4 (11% identical), Caenorhabditis elegans unc-39 (10% identical). Paralogues in human: SIX4 (19% identical), SIX5 (18% identical), SIX1 (15% identical), SIX2 (14% identical), SIX6 (14% identical), SIX3 (13% identical).
Diseases named in the same sentence as ANHX in open-access papers:
ANHX is named in the same sentence as 3 diseases in open-access papers, as found by Europe PMC text mining. Sharing a sentence is not in itself a finding about the gene and the disease. The quoted sentences say what the papers report.
psoriasis (2 papers, 2022 to 2025). An autoimmune condition characterized by red, well-delineated plaques with silvery scales that are usually on the extensor surfaces and scalp. "Our work proposed that STFs (PPARG, ZFPM2, ZNF415, HLX, and ANHX) mediate the initiation of chronic inflammation and metabolic disorders that increase the risk of developing AD in the psoriasis population." (PMID 35669784, 2022). "We identified 5 STFs (PPARG, ZFPM2, ZNF415, HLX, and ANHX) in common DEGs and investigated their potential roles in psoriasis and AD." (PMID 35669784, 2022). "Among these, four genes, PPARG, ZFPM2, ZNF415, and HLX, were down-regulated and ANHX upregulated in psoriasis and AD." (PMID 35669784, 2022). "Additionally, ZNF384 was identified as the key transcription factor that modulates the expression of PPARG, ZNF415, HLX, and ANHX, pointing to its potential as a therapeutic target for psoriasis and AD." (PMID 40343299, 2025). "PPARG, ZFPM2, ZNF415, and HLX were down-regulated in psoriasis and AD, while ANHX was up-regulated." (PMID 40343299, 2025). "The STFs (PPARG, ZFPM2, ZNF415, HLX, and ANHX) may increase the morbidity rate of AD in psoriasis by initiating a positive feedback loop of excessive inflammation and metabolic disorders." (PMID 35669784, 2022). "ZNF384 is a potential therapeutic target for psoriasis and AD by regulating PPARG, ZNF415, HLX, and ANHX." (PMID 35669784, 2022).
metabolic syndrome (1 paper, 2022). A cluster of metabolic risk factors for CARDIOVASCULAR DISEASES and TYPE 2 DIABETES MELLITUS. "ZNF384 is the potential transcription factor that may modulate STFs PPARG, ZNF415, HLX, and ANHX, thus subsequently triggering hyperinflammatory states and metabolic syndromes." (PMID 35669784, 2022).
ANHX also shares sentences with these, for which no sentence is quoted: metabolic disorders (1 paper).